TNFRSF21 (TNF receptor superfamily member 21)
Description:
Promotes apoptosis, possibly via a pathway that involves the activation of NF-kappa-B. Can also promote apoptosis mediated by BAX and by the release of cytochrome c from the mitochondria into the cytoplasm. Trophic-factor deprivation triggers the cleavage of surface APP by beta-secretase to release sAPP-beta which is further cleaved to release an N-terminal fragment of APP (N-APP). Negatively regulates oligodendrocyte survival, maturation and myelination. Plays a role in signaling cascades triggered by stimulation of T-cell receptors, in the adaptive immune response and in the regulation of T-cell differentiation and proliferation. Negatively regulates T-cell responses and the release of cytokines such as IL4, IL5, IL10, IL13 and IFNG by Th2 cells. Negatively regulates the production of IgG, IgM and IgM in response to antigens. May inhibit the activation of JNK in response to T-cell stimulation. Also acts as a regulator of pyroptosis: recruits CASP8 in response to reactive oxygen species (ROS) and subsequent oxidation, leading to activation of GSDMC.
Synonyms: CD358; DR6; BM-018
Tractability: Antibody: UniProt places it where antibodies can reach, with high confidence; its Gene Ontology location is reachable by antibodies, with high confidence; UniProt predicts a signal peptide or a membrane-spanning region; the Human Protein Atlas places it where antibodies can reach. PROTAC: ubiquitination databases record sites on it; its protein half-life has been measured.
Gene: Protein-coding gene on chromosome 6 (47,231,532 to 47,309,947, reverse strand). Ensembl gene ENSG00000146072.
Subcellular location: Cell membrane
Subcellular location (Human Protein Atlas): Cytosol; Plasma membrane
Pathways (Reactome):
Cellular responses to stimuli: Attenuation phase; HSF1 activation; HSF1-dependent transactivation; Regulation of HSF1-mediated heat shock response
Metabolism: PPARA activates gene expression
Gene Ontology:
Molecular function: protein binding
Biological process: apoptotic process; cellular response to tumor necrosis factor; negative regulation of myelination; adaptive immune response; B cell apoptotic process; humoral immune response; myelination; negative regulation of B cell proliferation; negative regulation of interleukin-10 production; negative regulation of interleukin-13 production; negative regulation of interleukin-5 production; negative regulation of T cell proliferation; neuron apoptotic process; oligodendrocyte apoptotic process; regulation of oligodendrocyte differentiation; T cell receptor signaling pathway; axonal fasciculation; signal transduction
Cellular component: plasma membrane
Genetic constraint (gnomAD): Loss-of-function variants: 19 observed, 46.12 expected, observed/expected ratio (o/e) 0.41, 90% interval 0.29 to 0.6. The upper end of that interval is the gene's LOEUF score, 0.6, which puts it in group 2 of 6, group 1 being the genes least tolerant of losing a copy. Missense variants: 737 observed, 854.07 expected, observed/expected ratio (o/e) 0.86, 90% interval 0.81 to 0.92. Synonymous variants: 314 observed, 338.67 expected, observed/expected ratio (o/e) 0.93, 90% interval 0.85 to 1.02.
Homologues: Orthologues: chimpanzee TNFRSF21 (99% identical), macaque TNFRSF21 (99% identical), rabbit TNFRSF21 (93% identical), pig TNFRSF21 (92% identical), dog TNFRSF21 (92% identical), rat Tnfrsf21 (89% identical), mouse Tnfrsf21 (89% identical), guinea pig TNFRSF21 (82% identical), tropical clawed frog tnfrsf21 (60% identical), zebrafish tnfrsf21 (54% identical). Paralogues in human: TNFRSF1B (14% identical), TNFRSF11A (14% identical), TNFRSF11B (13% identical), LTBR (13% identical), TNFRSF8 (13% identical), NGFR (12% identical), CD40 (11% identical), TNFRSF1A (11% identical), RELT (10% identical), TNFRSF6B (10% identical), TNFRSF9 (10% identical), TNFRSF10A (9% identical), and 9 more.
Diseases named in the same sentence as TNFRSF21 in open-access papers:
TNFRSF21 is named in the same sentence as 105 diseases in open-access papers, as found by Europe PMC text mining. Sharing a sentence is not in itself a finding about the gene and the disease. The quoted sentences say what the papers report.
ovarian carcinoma (15 papers, 2012 to 2025). A malignant neoplasm originating from the surface ovarian epithelium. "Studies have shown that TNFRSF21 is expressed at elevated levels in different tumor tissues, including prostate, breast and ovarian cancers." (PMID 36983630, 2023).
Alzheimer disease (6 papers, 2013 to 2024). A progressive, neurodegenerative disease characterized by loss of function and death of nerve cells in several areas of the brain leading to loss of cognitive function such as memory and language. "It has been reported that amyloid precursor protein binds with tumor necrosis factor receptor superfamily member 21 (TNFRSF21) to induce neural inflammation in Alzheimer’s disease." (PMID 36440278, 2022).
colon cancer (6 papers, 2010 to 2021). "A significant overlap was detected with several relevant gene families, including colon cancer progression (e.g., FN1, IGBP3, PLAUR and TIMP1; P=0.00052), tumour cell apoptosis (e.g., BID, TNFRSF21, PHLDA1 and NOTCH1; P=1.46 × 10–6) and cell proliferation (e.g., CTGF, SPP1, FOLR1 and SPARC)." (PMID 21119668, 2010).
lung carcinoma (6 papers, 2014 to 2025). "Our research findings provide insight into the fundamental processes TNFRSF21 supports in lung carcinoma CSCs." (PMID 40109864, 2025). "The prognostic value of TNFRSF21 expression in lung cancer was evaluated by the GEPIA and Kaplan-Meier Plotter databases." (PMID 40109864, 2025). "The identification of TNFRSF21 in LUAD enhances our understanding of lung cancer’s fundamental biology, offering insights into managing chemoresistance." (PMID 40109864, 2025). "TNFRSF21 plays a role in apoptosis induction, immune system regulation, and inhibiting immune evasion and metastasis in lung cancer." (PMID 40107973, 2025). "In our investigation, we observed that excessive TNFRSF21 expression stimulated lung cancer stem cell characteristics by promoting CD133 and CD44 mRNA expression." (PMID 40109864, 2025). "Suppression of TNFRSF21 significantly inhibited lung cancer cell progression, while inducing apoptosis." (PMID 40109864, 2025). "The production of ROS was found to participate in the inhibitory effects on lung cancer stem cells (CSCs), with decreased TNFRSF21 restraining ROS contents." (PMID 40109864, 2025). "Suppression of TNFRSF21 led to a reduction in the migratory and invasive capacities of lung cancer cells, suggesting the involvement of TNFRSF21 in LUAD." (PMID 40109864, 2025). "In summary, our study elucidates a mechanism whereby TNFRSF21 alters lung cancer cell fate by regulating CSC-like properties and ROS accumulation." (PMID 40109864, 2025). "Elevated TNFRSF21 expression correlated with an unfavorable prognosis in lung cancer patients." (PMID 40109864, 2025). "In conclusion, TNFRSF21 may act as a novel target for lung cancer chemotherapy, particularly for eradicating lung CSCs." (PMID 40109864, 2025). "We found elevated levels of TNFRSF21 in both lung cancer tissue samples and cells." (PMID 40109864, 2025). "Additionally, inhibiting TNFRSF21 decreased lung cancer cell growth and improved sensitivity to DDP." (PMID 40109864, 2025). "TNFRSF21 expression patterns in lung cancer tissues and cells were examined using RT-PCR assay." (PMID 40109864, 2025). "TNFRSF21 (DR6) is a receptor involved in regulating the immune response that contributes to malignant survival, promoting tumor aggressiveness in lung cancer by increasing ERK/FOXM1 signaling, and cancer stem cell characteristics by promoting CD133 and CD44 mRNA expression." (PMID 41440381, 2025). "We observed a significant elevation of TNFRSF21 in both LUAD patients and lung cancer cells." (PMID 40109864, 2025).
osteosarcoma (6 papers, 2012 to 2024). A usually aggressive malignant bone-forming mesenchymal neoplasm, predominantly affecting adolescents and young adults. "And the underlying mechanism of TNFRSF21 in osteosarcoma was further investigated." (PMID 38184626, 2024). "In this study, we demonstrated that TNFRSF21 acted as an inhibitory factor of osteosarcoma development by promoting necroptosis." (PMID 38184626, 2024). "Our data showed that osteosarcoma patients with high expression of TNFRSF21 had relatively higher survival rate." (PMID 38184626, 2024). "The Notch signaling pathway mediates the growth of osteosarcoma promoted by bone morphogenetic protein 9 (BMP9).24,25 Tumor necrosis factor receptor superfamily member 21 (TNFRSF21) overexpression induces cell death in osteosarcoma cells." (PMID 34342651, 2021). "We explored the effect of TNFRSF21 overexpression on osteosarcoma growth in vivo." (PMID 38184626, 2024). "Then the impact of TNFRSF21 on osteosarcoma cells was detected." (PMID 38184626, 2024). "As the functions of TNFRSF21 and necroptosis mediators were unknown in osteosarcoma, we further examined their expression levels." (PMID 38184626, 2024). "To test the hypothesis that TNFRSF21 promoted necroptosis in osteosarcoma, we examined the phosphorylation levels of RIPK1, RIPK3 and MLKL." (PMID 38184626, 2024). "Among the genes that constituted the signature, the role of TNFRSF21 in osteosarcoma was unclear." (PMID 38184626, 2024). "Overexpression of TNFRSF21 inhibited the growth and motility of osteosarcoma." (PMID 38184626, 2024). "Overexpression of TNFRSF21 inhibited proliferation and motility of osteosarcoma cells." (PMID 38184626, 2024). "The expression of TNFRSF21 was down-regulated in osteosarcoma cell lines." (PMID 38184626, 2024). "This suggested that TNFRSF21 activated necroptosis in osteosarcoma." (PMID 38184626, 2024). "The necroptosis prognostic signature and NS established in this study could be used as an independent prognostic factor, TNFRSF21 may be a necroptosis target in osteosarcoma therapy." (PMID 38184626, 2024). "Additionally, our findings suggest that TNFRSF21 could serve as a treatment target through necroptosis, offering a novel approach for osteosarcoma treatment." (PMID 38184626, 2024). "In addition, TNFRSF21 expression was positively correlated with necroptosis mediators, suggesting TNFRSF21 might promote necroptosis in osteosarcoma with better prognosis." (PMID 38184626, 2024). "However, the link between TNFRSF21 and immune cell in osteosarcoma needs to be further explored." (PMID 38184626, 2024). "Mechanically, TNFRSF21 upregulated the phosphorylation levels of RIPK1, RIPK3 and MLKL to promote necroptosis in osteosarcoma." (PMID 38184626, 2024). "However, the role of TNFRSF21 and the exactly mechanisms in mediating PCD in osteosarcoma is still not clarified." (PMID 38184626, 2024).
lung adenocarcinoma (5 papers, 2022 to 2025). A carcinoma that arises from the lung and is characterized by the presence of malignant glandular epithelial cells. "LncRNA MIR31HG can inhibit cuproptosis and promote the proliferation, migration, and invasion of lung adenocarcinoma cells by down-regulating miR-193a-3p and increasing downstream TNFRSF21 expression." (PMID 38839842, 2024). "According to the latest research from Mo’s team, MIR31HG serves as an oncogene by targeting mir-193a-3p and positively enhances recombinant tumor necrosis factor receptor superfamily, member 21 (TNFRSF21) expression in lung adenocarcinoma." (PMID 37636269, 2023). "We investigated the function of TNFRSF21 in lung adenocarcinoma (LUAD)." (PMID 40109864, 2025).
breast carcinoma (4 papers, 2014 to 2022). "In the analysis for RFS, differential expression of ZNF611, ZNF304, RIPK1, DUSP8, TNFRSF21 and HRAS genes was associated with outcome for breast cancer patients who received radiotherapy." (PMID 30938061, 2019).
glioma (4 papers, 2022 to 2025). A benign or malignant brain and spinal cord tumor that arises from glial cells (astrocytes, oligodendrocytes, ependymal cells). "There are some studies on the role of TNFRSF21 in tumors such as gastric cancer, pancreatic adenocarcinoma and glioma." (PMID 38184626, 2024).
head and neck squamous cell carcinoma (4 papers, 2020 to 2024). A squamous cell carcinoma that arises from any of the following anatomic sites: lip and oral cavity, nasal cavity, paranasal sinuses, pharynx, larynx, and salivary glands. "MiR‐20a‐5p targets TNFRSF21 to downregulate its expression, thus promoting cell proliferation, migration, and invasion capacities in head and neck squamous cell carcinoma." (PMID 35606813, 2022). "In head and neck squamous cell carcinoma (HNSCC), miR-20a-5p functioned as an oncogene by downregulating TNFRSF21 and upregulating CCR7 expression." (PMID 37829050, 2023).
melanoma (4 papers, 2016 to 2025). A malignant, usually aggressive tumor composed of atypical, neoplastic melanocytes. "TNFRSF21 demonstrated complex associations: positive with Tregs and macrophages, but negative with NK cells and eosinophils, particularly in primary melanomas." (PMID 40943183, 2025). "Eleven genes—including TNFRSF21 and SPP1—were markedly upregulated in tumors, suggesting active angiogenic signaling that may drive melanoma progression and metastasis." (PMID 40943183, 2025).
pancreatic adenocarcinoma (4 papers, 2023 to 2025). "Pancreatic adenocarcinoma shows a notable increase in TNFRSF21, and its absence provides significant survival benefits." (PMID 40109864, 2025). "Lower expression of TNFRSF21 had a prominent advantage in survival and was correlated with a low level of immune infiltration in pancreatic adenocarcinoma." (PMID 36807122, 2023).
cervical carcinoma (2 papers, 2014 to 2015). A carcinoma arising from either the exocervical squamous epithelium or the endocervical glandular epithelium. "In addition, initial experiments following TNFRSF21 discovery showed that ectopic expression of this death receptor induced apoptosis in HeLa S3 cervical carcinoma cells." (PMID 24955130, 2014).
cognitive decline (2 papers, 2013 to 2025). "Enhanced Tnfrsf21‐App interactions between MOL2 and ExN‐L6‐CT‐2 exacerbated neuroinflammation and cognitive decline." (PMID 40546220, 2025).
lupus (2 papers, 2017 to 2025). "Here we show expression of an orphan immune regulator, death receptor 6 (DR6/TNFRSF21), on a population of Tfh cells that are highly expanded in lupus-like disease progression in mice." (PMID 28045014, 2017). "Although the murine Tnfrsf21 gene (on chromosome 17) is not in murine SLE-associated loci, the unique characteristics of the lupus CD4+ T cell populations emphasize the importance of DR6 functions in the regulation of CD4+ T cells in lupus-prone mice." (PMID 28045014, 2017).
mastitis (2 papers, 2019 to 2021). Inflammation of breast tissue during lactation or postpartum due to an obstructed duct or infection. "The TNFRSF21 was identified to be involved in the regulation of bovine mastitis susceptibility via GWAS." (PMID 34449805, 2021). "More recently, a role for the TNFRSF21 in the regulation of bovine mastitis susceptibility via GWAS and post-transcriptional analysis was discovered." (PMID 34449805, 2021). "TNFRSF21 was up-regulated suggesting that TNFRSF21 is an important candidate gene associated with mastitis susceptibility traits." (PMID 31447828, 2019). "Taken together, these results provided strong evidence for the study of SNPs in bovine mastitis, and revealed the role of SYK, PTK2B, and TNFRSF21 in bovine mastitis susceptibility/tolerance." (PMID 31447828, 2019). "In bPBLs and bMECs, PTK2B, SYK, and TNFRSF21 are involved in different mechanisms of immune responses associated with mastitis." (PMID 31447828, 2019). "The LD block data also showed that there were strong LD relationship between rs75762330 and PTK2B, rs88640083 and SYK, rs20438858 and TNFRSF21, suggesting that these three immune-regulated genes are important candidate genes associated with mastitis traits in Chinese Holstein cows." (PMID 31447828, 2019). "We used two-stage correlation analysis to find 27 significant SNPs associated with risk of mastitis, among which three SNPs (rs75762330, rs88640083, and rs20438858) were annotated to immune-regulated genes (PTK2B, SYK, and TNFRSF21)." (PMID 31447828, 2019). "It showed that expression of SYK and PTK2B was down-regulated significantly (P < 0.001) in mastitis cows in comparison to the control group, while TNFRSF21 was up-regulated." (PMID 31447828, 2019). "TNFRSF21 was significantly up-regulated in bPBLs of mastitis cows and LPS-stimulated bMECs, indicating that TNFRSF21 plays an important role in bovine mastitis inflammation." (PMID 31447828, 2019). "Importantly, PTK2B and SYK expression was down-regulated in both peripheral blood leukocytes (PBLs) of clinical mastitis cows and in vitro LPS (E. coli)–stimulated bovine mammary epithelial cells, while TNFRSF21 was up-regulated." (PMID 31447828, 2019). "Therefore, we hypothesized that SYK and TNFRSF21 may be involved in the NF-κB pathway, stimulating IL-1β secretion and promote mastitis inflammation in both bPBLs and bMECs." (PMID 31447828, 2019).
panic disorder (2 papers, 2023). An anxiety disorder characterized by multiple unexpected panic attacks with persistent concern of recurring attacks. "Variants in TNFRSF21, one of the targets of miR-584-5p, which was decreased in MDD and ANX in our study, were previously associated with MDD (rs188552424) and a statistical trend toward an association with panic disorder (rs2103868) in GWAS." (PMID 36746925, 2023). "The TNFRSF21 gene has been found to be differentially expressed in PTSD, including in postmortem brain samples in orbitofrontal cortex and dorsal anterior cingulate cortex regions, and genetic variants within this gene have emerged in genome-wide association studies of panic disorder and depression." (PMID 36631443, 2023).
periodontitis (2 papers, 2022 to 2025). An acute or chronic inflammatory process that affects the tissues that surround and support the teeth. "The enrichment of TNFRSF21+ fibroblasts with high expression of CXCL1, CXCL2, CXCL5, CXCL6, CXCL13, and IL24 was detected in patients with periodontitis compared to healthy individuals." (PMID 35154475, 2022).
allergic asthma (1 paper, 2022). A asthma with a basis in a pathological type I hypersensitivity reaction. "Similar to knockout mice with allergic asthma, it is possible that animals affected with FEK have an abnormal NF-kappa-B activation due to defective expression of TNFRSF17 and TNFRSF21 genes, as suggested by the current GWAS study." (PMID 35782544, 2022).
angioimmunoblastic T-cell lymphoma (1 paper, 2021). A mature T-cell non-Hodgkin lymphoma, characterized by systemic disease and a polymorphous infiltrate involving lymph nodes and extranodal sites. "Intriguingly, impairment of TNFRSF21/DR6 was previously implicated in increased cellular division and reduced apoptosis rates in B-cells and T-cell malignancies, including angioimmunoblastic T-cell lymphoma, another, recurrently EBV-driven type of cancer." (PMID 34039950, 2021).
Cognitive impairment (1 paper, 2025). Abnormal cognition is characterized by deficits in thinking, reasoning, or remembering. "Prolonged hypoxia triggers Rps29‐Bax‐mediated apoptosis and Tnfrsf21‐App‐driven neuroinflammation, culminating in myelin loss and cognitive impairment." (PMID 40546220, 2025). "Consequently, disturbing the Tnfrsf21‐App interaction may potentially exert protective effects in HACE‐induced cognitive impairment." (PMID 40546220, 2025).
diabetic nephropathy (1 paper, 2023). "Increased expression of TNFRSF21 is considered a urinary biomarker of diabetic nephropathy progression." (PMID 37569434, 2023).
endometrial carcinoma (1 paper, 2023). A malignant tumor arising from the epithelium that lines the cavity of the uterine body. "Exons 2 and 3 of TNFRSF21 transcripts were back-spliced to produce circTNFRSF21 that can promote endometrial carcinoma pathogenesis by regulating the miR-1227-MAPK13/ATF2 axis." (PMID 38139387, 2023).